E2F7 (E2F transcription factor 7)
Diseases named in the same sentence as E2F7 in open-access papers (continued):
Sharing a sentence is not in itself a finding about the gene and the disease.
glioma (continued). "To further delineate the regulatory mechanism of DDX11-AS1/miR-1183 in glioma development, we performed a bioinformatics analysis and found that miR-1183 could potentially bind to the E2F7 mRNA 3′UTR region." (PMID 41050080, 2025). "Here, miR-1183 was shown to directly target E2F7, exerting a tumor-promoting role in glioma." (PMID 41050080, 2025). "The tumor-promoting effect of E2F7 was also reported in glioma." (PMID 41050080, 2025). "The authors described that the overexpression of miR-545, a known target of circPRKCI, could inhibit the expression of the transcription factors E2F7 and retinoic acid-inducible gene-I, and the progression of glioma cells." (PMID 38741779, 2024). "Thus, we detected the expression of E2Fs in HOTAIRM1-overexpressed tMSCs and found that E2F7, which has been reported to act as an oncogene in glioma, was also obviously increased." (PMID 35586206, 2022). "Our study revealed that the HOTAIRM1/FUS/E2F7 axis is involved in the malignant progression of tMSCs transformed by GSCs in the glioma microenvironment and may function as a novel target for glioma therapy." (PMID 35586206, 2022). "Collectively, this study revealed that the HOTAIRM1/FUS/E2F7 axis is involved in the maintenance of the malignant phenotype of tMSCs and may function as a novel target for glioma therapy." (PMID 35586206, 2022). "In conclusion, we report that HOTAIRM1 is conducive to maintaining the malignant phenotype of tMSCs transformed by GSCs in the glioma microenvironment via E2F7 by binding to FUS and that the HOTAIRM1/FUS/E2F7 axis may be a potential target for glioma therapy." (PMID 35586206, 2022). "Intriguingly, E2F7 was indicated to highly expressed in gliomas tissues." (PMID 33637098, 2021). "A low level of E2F7 predicted poor survival of patients with glioma and might constitute a potential therapeutic target for glioma." (PMID 35201478, 2021). "In addition, based on different brain studies in the Oncomine dataset, E2F7 was frequently up-regulated in glioblastoma (high-grade glioma), compared with normal tissues and oligodendroglioma (low-grade glioma)." (PMID 32814835, 2020). "However, there is increasing evidence that E2F7 can promote cancer cell proliferation including in glioma." (PMID 32039732, 2020). "We next explored the prognostic implication of E2F7 in glioma and glioblastoma." (PMID 32814835, 2020). "Importantly, inhibition of autophagic flux induced by miR-129 or E2F7 rescued the proliferation of glioma cells." (PMID 26824182, 2016). "Interestingly, enforced expression of miR-129 or inhibition of Notch-1 increased the expression of E2F7 in glioma cells." (PMID 26824182, 2016). "Importantly, E2F7 could be an independent prognostic factor of gliomas, whose overexpression predicts poor prognosis in glioma patients." (PMID 31409777, 2019). "In the present study, we first showed that E2F7 could trigger autophagic flux in glioma." (PMID 26824182, 2016). "In this study, we comprehensively evaluated the role of lncRNA DDX11-AS1 in glioma development and suggested a novel DDX11-AS1/miR-1183/E2F7 axis in the pathogenesis of glioma, providing us with a potential therapeutic target in glioma." (PMID 41050080, 2025). "A distinct glioma stem cell population was identified, characterized by high proliferative potential and an enrichment of E2F1, E2F2, E2F7, and BRCA1 regulons, with implications for tumor growth and patient outcomes." (PMID 39981232, 2025). "In this study, circPRKCI acted as a ceRNA to inhibit the tumor-suppressive miR-545 and increased the expression of the downstream gene E2F7/RIG-1, which eventually promoted the progression of glioma." (PMID 38741779, 2024). "Consistent with the results in endometrial cancer and glioma, we discovered that E2F7 executed roles in facilitating OSCC cell growth and invasion, together indicating that E2F7 is an oncogene." (PMID 33637098, 2021).
glioma (continued). "E2F5, E2F7, and E2F8 were significantly upregulated in brain and CNS cancers relative to normal brain samples, while E2F1 and E2F3 were more highly expressed in normal brain samples in the ONCOMINE dataset." (PMID 34617871, 2021). "Here, in A172 and primary human glioma cells ectopic miR-545 overexpression significantly downregulated RIG-1 and E2F7, both were upregulated with miR-545 inhibition." (PMID 31409777, 2019). "As a pro-tumorigenic transcriptional factor, although elevated E2F7 expression was found in gliomas, the impacts of E2F7 in OSCC are still not fully investigated in depth." (PMID 33637098, 2021). "E2F7, PTX3, and VAV3 have been reported as oncogene in many kinds of tumors especially in glioma." (PMID 34222249, 2021). "Thus, in line with the in vitro findings, circPRKCI shRNA induced miR-545 accumulation, E2F7 and RIG-1 downregulation in subcutaneous A172 glioma tumors." (PMID 31409777, 2019).
lung carcinoma (17 papers, 2017 to 2025). "E2F7 was shown to function as a tumor inducer in several cancer types, including lung cancer, hepatocellular cancer and gallbladder cancer." (PMID 41050080, 2025). "E2F transcription factor 7 (E2F7) is considered to be an oncogene that inhibits apoptosis and promotes proliferation and metastasis of lung cancer cells." (PMID 40296912, 2025). "In vivo experiments corroborated these findings, showing reduced tumor growth and lung metastasis upon E2F7 suppression in lung cancer models." (PMID 38760774, 2024). "Together, these findings demonstrate that E2F7 knockdown significantly impedes lung cancer progression and metastasis, underscoring its potential as a therapeutic target in LUAD." (PMID 38760774, 2024). "E2F7 and ANLN, were both involved in the cell cycle process and associated with cell proliferation in malignancy lung cancer." (PMID 38711158, 2024). "Overexpression and oncogenic function of E2F7 have been well established in cancers, including lung cancer, rectal adenocarcinoma, papillary thyroid cancer, esophageal cancer, and gastric cancer." (PMID 35201478, 2021). "Studies have shown that inhibition of E2F transcription factor 7 (E2F7) expression can inhibit the viability of lung cancer cells, inhibit the formation, migration, and invasion of tumor colonies, and promote tumor-cell apoptosis." (PMID 33988228, 2021). "Recent researches show the various non-coding RNA can influence the progress of lung cancer by regulating the expression of E2F7." (PMID 34721973, 2021). "It was also found that downregulation of E2F7 by miRNA-302a/d decreased proliferation of hepatocellular carcinoma cells and significantly inhibited stemness of lung cancer stem cells by targeting the E2F7/AKT/β-catenin/CCND1 signaling pathway." (PMID 33061852, 2020). "Furthermore, inhibiting E2F7 in lung cancer cells markedly reduced their proliferation, migration, invasion, and increased apoptosis." (PMID 38760774, 2024). "The antitumor effect of E2F7 knockdown was evaluated in vivo using the LLC mouse lung cancer model." (PMID 38760774, 2024). "The E2F7 transcription factor has been confirmed to be related to the occurrence and development of a variety of solid tumors, but the relationship with the prognosis of lung cancer is still unclear." (PMID 35984189, 2022). "Moreover, in vivo tests indicated that lowering E2F7 levels could reduce the growth and spread of lung cancer tumors." (PMID 38760774, 2024). "In lung cancer, the anti-tumor effects of miR-383 could be partly explained by E2F7 suppression." (PMID 36313570, 2022). "Therefore, the different mechanisms of hsa_circ_0007580 and circPRKCI in lung cancer may due to different functions of E2F7 and PRKCA." (PMID 32681720, 2020). "In lung cancer cells, upregulation of circ-CCS resulted in the overexpression of E2F7, which promotes cell expansion." (PMID 36313570, 2022). "Metformin down-regulated four E2F family members, E2F1, E2F2, E2F7, and E2F8 in lung cancer cells, with E2F8 being the most prominently down-regulated one." (PMID 29254182, 2017).
hepatocellular carcinoma (15 papers, 2016 to 2025). A malignant tumor that arises from hepatocytes. "Has-miR-424-5p functions as a tumor suppressor microRNA in hepatocellular carcinoma (HCC) by inhibiting cell proliferation through targeting specific genes like E2F7." (PMID 40033232, 2025). "LncRNA MYLK-AS1 was verified to promote hepatocellular carcinoma angiogenesis by targeting miR-424-5p/E2F7 axis and induce VEGFR-2 expression." (PMID 36384673, 2022). "This study also clarified the effects of E2F7 on malignant behavior and angiogenesis-related factors of hepatocellular carcinoma." (PMID 35444695, 2022). "Previously we developed E2f7 and E2f8 transgenic (Tg) mice capable of blocking the proliferation of chemically-induced hepatocellular carcinomas, consistent with their role as tumor suppressors in the liver." (PMID 33922435, 2021). "As expected, a negative correlation between miRNA-302a/d expression and the levels of E2F7 was observed in CD133+/EpCAM1+ hepatoma cells." (PMID 30326936, 2018). "For example, in hepatocellular carcinoma cell lines, hypoxia could induce E2F7 expression and promote sirolimus resistance." (PMID 38013642, 2024). "Moreover, a cluster of CD133+/EpCAM1+ hepatoma cells, which have been considered liver CSCs, exhibited enhanced E2F7 expression compared with the CD133−EpCAM− cells." (PMID 30326936, 2018). "This study aims to explore the mechanism of the miR-424-5p/E2F7 axis in hepatocellular carcinoma (HCC) and provide new ideas for targeted therapy of HCC." (PMID 33201900, 2020). "LncRNA MYLK-AS1 stimulating neovascularization by regulating miR-424-5p/E2F7 axis and activating VEGFR-2 signal transduction pathway in hepatocellular carcinoma." (PMID 36384673, 2022).
glioblastoma (13 papers, 2018 to 2024). The most malignant astrocytic tumor (WHO grade IV). "E2F7 was found to be up-regulated in glioblastoma patients, and high E2F7 expression was associated with poor overall survival in glioblastoma patients." (PMID 32814835, 2020). "High invasiveness is an important cause of difficult treatment of glioblastoma; we performed transwell assays to determine whether E2F7 is essential for cell migration and invasion in vitro." (PMID 32814835, 2020). "Overall, E2F7 is responsible, in part, for the proliferative advantages in glioblastoma mediated by EZH2 inhibition of PTEN and leading to activation of the PI3K/AKT/mTOR pathway." (PMID 38183103, 2024). "E2F7 has been identified as a cancer-promoting gene in glioblastoma, liver cancer, and colon cancer." (PMID 38760774, 2024). "E2F7 is an atypical E2F factor that can promote the proliferation and migration of liver cancer and glioblastoma." (PMID 35444695, 2022). "The Murat Brain Statistics showed that E2F7 was also increased in glioblastoma (fold change = 4.632) compared to normal samples." (PMID 33381564, 2020). "In this study, using the online database, patient specimens and in vitro and in vivo models, we studied the genetic alteration, clinical value and biological effects of E2F7 in glioblastoma." (PMID 32814835, 2020). "Western blot showed that phosphorylation of AKT at Ser473, mTOR at Ser2448, was decreased in glioblastoma cells with E2F7 knockdown and increased in cells with E2F7 overexpression." (PMID 32814835, 2020). "The newly identified E2F7/EZH2/PTEN axis is a promising target for clinical intervention of glioblastoma." (PMID 32814835, 2020). "We also demonstrated, for the first time, that E2F7 is involved in PTEN/AKT/mTOR pathway through regulating EZH2 in glioblastoma." (PMID 32814835, 2020). "MTT assay, colony formation, cell-cycle assay, cell metastasis and the in vivo model were employed to determine the functional role of E2F7 in glioblastoma." (PMID 32814835, 2020). "All the results suggest that E2F7 serves as a promising marker for prognosis of glioblastoma patients." (PMID 32814835, 2020). "Our data suggest that E2F7 functions as an oncogene to promote glioblastoma progression and serves as a promising target for anti-glioblastoma treatment." (PMID 32814835, 2020). "We also examined the expression of E2F7 in glioblastoma cell lines; E2F7 expression level was higher in glioblastoma cell lines than in normal glial cell SVGP12." (PMID 32814835, 2020). "Moreover, E2F7 acts upstream of EZH2 as a transcriptional activator in glioblastoma by binding to its promoter." (PMID 38183103, 2024). "In addition, in certain tumor cell lines, particularly those derived from hematopoietic and lymphoid malignancies and clinical diseases, such as glioblastoma, E2F7 is expressed at very low levels." (PMID 35628184, 2022). "Our data suggest that E2F7 serves as a promising marker for prognosis of glioblastoma patients." (PMID 32814835, 2020). "We determined whether E2F7 was a regulator for transcription of PTEN in glioblastoma cells; the results showed that the mRNA level of PTEN was significantly increased after E2F7 knockdown." (PMID 32814835, 2020). "Inversely, overexpression of E2F7 promoted cell-cycle progression in glioblastoma." (PMID 32814835, 2020). "In the present study, E2F7 triggered the AKT/mTOR pathway by inhibiting PTEN in glioblastoma." (PMID 32814835, 2020). "Invasion assays showed that E2F7 was essential for cell invasion in glioblastoma cells." (PMID 32814835, 2020). "In addition, in the Sun Brain Statistics, E2F7 was overexpressed in glioblastoma (fold change = 5.823), and in the French Brain Statistics, the increased E2F7 expression was found in anaplastic oligodendroglioma compared to normal sample (fold change = 2.282)." (PMID 33381564, 2020). "E2F7 is an atypical E2F factor, and its role in glioblastoma remains undefined." (PMID 32814835, 2020).
glioblastoma (continued). "In addition, we explored the mechanistic role of E2F7−EZH2 axis in AKT/mTOR activation, and the results suggested that E2F7 promoted glioblastoma progression via EZH2-mediated PTEN/AKT pathway." (PMID 32814835, 2020). "In summary, we showed that up-regulation of E2F7 in glioblastoma was closely correlated with poor prognosis, highlighting the importance of E2F7 in promoting cell proliferation, cell metastasis and tumorigenesis in glioblastoma." (PMID 32814835, 2020). "In addition, the knockdown of E2F7 significantly inhibited the binding of E2F7 with EZH2 promoter in glioblastoma cells." (PMID 32814835, 2020). "In addition, wound-healing assay showed that the migratory ability of glioblastoma cells with E2F7 knocked down was significantly lower than that of the control cells." (PMID 32814835, 2020). "Moreover, silencing PTEN attenuated the potency of E2F7 knockdown in glioblastoma cells." (PMID 32814835, 2020). "Enhanced E2F7 expression is also found in many types of cancer and a predictor of poor prognosis, e.g., in OSCC and glioblastoma patients, and for E2F1/2/7/8 also in cervical cancer patients." (PMID 35063803, 2022). "To evaluate the correlation of E2F7 and EZH2 expression in glioblastoma specimens, we analysed the data from TCGA." (PMID 32814835, 2020). "Collectively, our findings indicate that E2F7 promotes cell proliferation, cell metastasis and tumorigenesis via EZH2-mediated PTEN/AKT/mTOR pathway in glioblastoma." (PMID 32814835, 2020). "However, the clinical significance of E2F7 and its role in glioblastoma remains unclear." (PMID 32814835, 2020). "To further examine the binding site of E2F7 in EZH2 promoter, we performed a ChIP-qPCR analysis to locate the E2F7-binding site on EZH2 promoter in glioblastoma cells." (PMID 32814835, 2020). "Furthermore, a recent study identified the expression of E2F7 activating the transcription of enhancer of zeste homolog 2 (EZH2), thus inducing mTOR signalling in glioblastoma progression." (PMID 39348343, 2024). "In addition, based on the analysis of glioblastoma patient specimens, we found that EZH2 expression was positively correlated with E2F7, and high expression of EZH2 was correlated with poor patient prognosis." (PMID 32814835, 2020). "In this study, we showed that E2F7 was highly expressed and correlated with poor prognosis in glioblastoma, whereas E2F7 expression was not correlated with IDH status, sex, chemotherapy and radiotherapy." (PMID 32814835, 2020).
gallbladder cancer (12 papers, 2018 to 2025). "In gallbladder cancer cells, karyopherin α2 increased the nuclear localization of E2F7 to promote E2F7-mediated transcriptional repression." (PMID 39613162, 2024). "Previous studies have proved that miR-30a-5p prevents tumor migration and metastasis by targeting E2F7 in gallbladder cancer." (PMID 33828913, 2021). "In gallbladder carcinoma, E-cadherin and vimentin protein levels were affected by miR-30a-5p depletion, and these influences were partly weakened by E2F7 suppression." (PMID 33637098, 2021). "Findings obtained from a previous study suggest that E2F1 and E2F7 have different regulatory effects on KPNA2 to promote the development of gallbladder cancer." (PMID 33489876, 2020). "In gallbladder cancer, miR-30a could directly target E2F7 (encoding E2F transcription factor 7) to regulate epithelial-mesenchyme transition (EMT) and metastasis, and participated in cancer progression." (PMID 35246136, 2022). "Moreover, KPNA2 promotes tumor development through the nuclear localization of E2F1 and E2F7 in gallbladder cancer." (PMID 34903711, 2021). "Additionally, KPNA2 promotes gallbladder cancer progression by regulating the nuclear localization of E2F1 and E2F7." (PMID 40830912, 2025).
colorectal cancer (10 papers, 2019 to 2026). A primary or metastatic malignant neoplasm that affects the colon or rectum. "In consistent with our study, an existing study elicited an overexpression of E2F7 in colorectal cancer cells and tissues where it could mediate MAPK/ERK signaling." (PMID 35383161, 2022). "miR‐424‐5p was shown to promote proliferation and metastasis of colorectal cancer cells by targeting SCN4B and also to inhibit cell proliferation by targeting E2F7, Cyclin E1, Cyclin A2, and Cyclin D1." (PMID 40405535, 2025). "Overexpression of LINC00174 promotes the proliferation, migration, and invasion of colorectal cancer cells by regulating Mir-1910-3p/TAZ and Mir-3127-5p/E2F7 signaling pathways." (PMID 34692467, 2021).
gastric cancer (10 papers, 2015 to 2026). A primary or metastatic malignant neoplasm involving the stomach. "The oncogenic effects of E2F family genes (E2F1 and E2F7) in gastric cancer were at least partially mediated through transcriptional activation of MYBL2." (PMID 41491570, 2026). "Circ0008035/miR-302a/E2F7 regulated apoptosis and ferroptosis in gastric cancer cells, which enhanced the inhibitory effect of dexmedetomidine on the occurrence and development of gastric cancer." (PMID 39314750, 2024). "CircRNA circ0008035 increases the expression of E2F transcription factor 7 (E2F7) by blocking miR-302a, inhibiting dexmedetomidine-induced ferroptosis in gastric cancer cells." (PMID 37686142, 2023). "miR‐30e also interacts with other lncRNAs to negatively regulate cancer progression such as oncogenic lncRNA DLEU2 that promoted esophageal cancer through the miR‐30e/E2F7 axis and MALAT1 which acted as a molecular sponge of miR‐30e to regulate ATG5 expression and autophagy in gastric cancer." (PMID 35612714, 2022). "Furthermore, miRNAs (miR-125a-5p, miR-331–3p, miR-17, miR-150, miR-155, miR-27b, miR-31, miR-92a and miR-509–5p), which differentially expressed in gastric cancer, were found to regulate expression of E2F1, E2F2, E2F5 and E2F7 in this study." (PMID 25646628, 2015). "Furthermore, miRNAs differentially expressed in gastric cancer were able to regulate expression of E2F1, E2F2, E2F5 and E2F7, indicating that miRNAs-altered expression of E2Fs proteins is important factors in gastric cancer development or progression." (PMID 25646628, 2015).